GNAQ (G protein subunit alpha q)
Description:
Guanine nucleotide-binding proteins (G proteins) function as transducers downstream of G protein-coupled receptors (GPCRs) in numerous signaling cascades. The alpha chain contains the guanine nucleotide binding site and alternates between an active, GTP-bound state and an inactive, GDP-bound state. Signaling by an activated GPCR promotes GDP release and GTP binding. The alpha subunit has a low GTPase activity that converts bound GTP to GDP, thereby terminating the signal. Both GDP release and GTP hydrolysis are modulated by numerous regulatory proteins. Signaling is mediated via phospholipase C-beta-dependent inositol lipid hydrolysis for signal propagation: activates phospholipase C-beta: following GPCR activation, GNAQ activates PLC-beta (PLCB1, PLCB2, PLCB3 or PLCB4), leading to production of diacylglycerol (DAG) and inositol 1,4,5-trisphosphate (IP3). Required for platelet activation (By similarity). Regulates B-cell selection and survival and is required to prevent B-cell-dependent autoimmunity (By similarity). Regulates chemotaxis of BM-derived neutrophils and dendritic cells (in vitro) (By similarity). Transduces FFAR4 signaling in response to long-chain fatty acids (LCFAs). Together with GNA11, required for heart development (By similarity).
Synonyms: GAQ; G-ALPHA-q; CMAL; SWS
Tractability: Small molecule: a structure with a bound ligand is known; a high-quality ligand is known. Antibody: UniProt places it where antibodies can reach, with high confidence; its Gene Ontology location is reachable by antibodies, with high confidence. PROTAC: ubiquitination databases record sites on it; its protein half-life has been measured; a small molecule that binds it is known.
Target class: Other membrane protein
Gene: Protein-coding gene on chromosome 9 (77,716,097 to 78,031,972, reverse strand). Ensembl gene ENSG00000156052.
Subcellular location: Cell membrane; Golgi apparatus; Nucleus; Nucleus membrane
Subcellular location (Human Protein Atlas): Nuclear speckles; Plasma membrane; Cytosol
Pathways (Reactome):
Hemostasis: ADP signalling through P2Y purinoceptor 1; Thrombin signalling through proteinase activated receptors (PARs); Thromboxane signalling through TP receptor
Signal Transduction: G alpha (q) signalling events; G-protein activation; PLC beta mediated events
Cellular responses to stimuli: High laminar flow shear stress activates signaling by PIEZO1 and PECAM1:CDH5:KDR in endothelial cells; Turbulent (oscillatory, disturbed) flow shear stress activates signaling by PIEZO1 and integrins in endothelial cells
Metabolism: Acetylcholine regulates insulin secretion; Fatty Acids bound to GPR40 (FFAR1) regulate insulin secretion
Metabolism of proteins: Cooperation of PDCL (PhLP1) and TRiC/CCT in G-protein beta folding
Gene Ontology:
Molecular function: G protein activity; GTPase activator activity; GTPase activity; protein binding; G protein-coupled receptor binding; G-protein beta/gamma-subunit complex binding; GTP binding; guanyl nucleotide binding
Biological process: cellular response to acidic pH; G protein-coupled receptor signaling pathway; hormone-mediated signaling pathway; mast cell degranulation; neuropeptide signaling pathway; phospholipase C-activating G protein-coupled receptor signaling pathway; phospholipase C-activating serotonin receptor signaling pathway; phospholipase C-activating tachykinin receptor signaling pathway; positive regulation of gonadotropin secretion; protein stabilization; regulation of canonical Wnt signaling pathway; response to prostaglandin E; sensory perception of itch; adenylate cyclase-activating G protein-coupled receptor signaling pathway; blood coagulation; entrainment of circadian clock; G protein-coupled acetylcholine receptor signaling pathway; glucose homeostasis; glutamate receptor signaling pathway; phototransduction, visible light; positive regulation of membrane depolarization; regulation of platelet activation; signal transduction
Cellular component: cytoplasmic side of plasma membrane; extracellular exosome; Golgi apparatus; lysosomal membrane; plasma membrane; postsynaptic cytosol; cytoplasm; nuclear membrane; nucleus; photoreceptor outer segment
Genetic constraint (gnomAD): Loss-of-function variants: 3 observed, 9.48 expected, observed/expected ratio (o/e) 0.32, 90% interval 0.14 to 0.82. That is too few expected variants to judge how well the gene tolerates losing a copy. Missense variants: 73 observed, 167.21 expected, observed/expected ratio (o/e) 0.44, 90% interval 0.36 to 0.53. Synonymous variants: 67 observed, 68.91 expected, observed/expected ratio (o/e) 0.97, 90% interval 0.8 to 1.19.
Cancer hallmarks: proliferative signalling (promotes)
Homologues: Orthologues: chimpanzee GNAQ (100% identical), macaque GNAQ (100% identical), pig GNAQ (100% identical), rat Gnaq (99% identical), zebrafish gnaq (93% identical), dog GNAQ (90% identical), rabbit GNAQ (88% identical), guinea pig GNAQ (87% identical), Drosophila melanogaster CG30054 (68% identical), zebrafish gna14 (68% identical), Drosophila melanogaster CG17760 (63% identical), Drosophila melanogaster Galphai (50% identical), and 15 more. Paralogues in human: GNA11 (90% identical), GNA14 (81% identical), GNA15 (57% identical), GNAI1 (52% identical), GNAI3 (52% identical), GNAT2 (51% identical), GNAI2 (51% identical), GNAO1 (49% identical), GNAT1 (49% identical), GNAT3 (49% identical), GNA13 (47% identical), GNAZ (47% identical), and 3 more.
Diseases named in the same sentence as GNAQ in open-access papers:
GNAQ is named in the same sentence as 196 diseases in open-access papers, as found by Europe PMC text mining. Sharing a sentence is not in itself a finding about the gene and the disease. The quoted sentences say what the papers report.
uveal melanoma (179 papers, 2010 to 2026). A melanoma derived from melanocytes of the uveal tract. "Opposed to skin melanomas, B-Raf Proto-Oncogene (BRAF) mutations are uncommon in uveal melanoma, while G Protein Subunit Alpha Q (GNAQ) and G Protein Subunit Alpha 11 (GNA11) gene mutations are very frequent." (PMID 40566630, 2025). "Most uveal melanoma cases are driven by activating mutations in GNAQ and GNA11 genes, which convey oncogenic signaling through the mitogen-activated protein kinase (MAPK) pathway." (PMID 41154654, 2025). "The ERK family kinases are MAPK signaling components downstream of MEK1/2, and ERK activation in uveal melanoma has been observed in relation to GNAQ and GNA11 mutations." (PMID 38683104, 2024). "In non-uveal melanomas, GNAQ/GNA11 mutations display a unique genetic profile characterized by a lower tumor mutational burden and fewer UV signature mutations than are common in cutaneous melanomas." (PMID 38474231, 2024). "Alternative genetic mechanism activating the MAPK pathway involves mutations in the GNAQ gene which have been described in uveal melanoma, blue nevi, Nevi of Ota and Spitz nevi." (PMID 38509523, 2024). "Uveal melanoma (UM), while exhibiting unique morphological features, shares considerable molecular disruptions with other conditions driven by GNAQ or GNA11 mutations." (PMID 39518110, 2024). "The majority of uveal melanomas have mutations in GNAQ or GNA11 leading to activation of the MAPK pathway." (PMID 38683104, 2024). "Mutations in the same residue (Q209) of the paralogue gene GNAQ were found in 22% of uveal melanoma metastases, 45% of primary uveal melanomas, and 55% of blue nevi." (PMID 39518110, 2024). "Activating mutations in GNAQ/GNA11 occur in over 90% of uveal melanomas (UMs), the most lethal melanoma subtype; however, targeting these oncogenes has proven challenging and inhibiting their downstream effectors show limited clinical efficacy." (PMID 38233483, 2024). "Uveal melanomas (UMs) frequently harbor mutations in GNAQ or GNA1133,34, both of which encode G protein subunits." (PMID 39349825, 2024). "Spitz melanomas show tyrosine kinase or serine-threonine kinase fusions, and melanomas in blue nevi and uveal melanomas often contain GNA11 or GNAQ mutations." (PMID 38474231, 2024). "Activating mutations in GNAQ gene (G alpha q gene) especially residing at codon 209 have been reported in uveal melanomas." (PMID 38509523, 2024). "Greater than 80% of uveal melanomas have a mutation in GNAQ or GNA11 which lead to downstream signaling through the MAPK pathway." (PMID 38683104, 2024). "Uveal melanoma (UM), recognized as the most prevalent primary intraocular malignancy in adults, is primarily driven by mutations in the GNAQ and GNA11 genes." (PMID 39518110, 2024). "For instance, the GNAQ mutation frequency is approximately 80–90% in uveal melanoma, and the p.Q209 (glutamine 209) mutation triggers a loss of GTPase activity, enabling permanent and oncogenic downstream signaling." (PMID 37240145, 2023). "They differ, for instance, in the oncogenic driver mutations, mainly alterations in MAPK signaling in cutaneous melanoma and alterations in GNAQ/GNA11 signaling or the BRCA1-associated protein BAP1 in uveal melanomas." (PMID 37577930, 2023). "Uveal melanoma is driven by oncogenic mutations in the heterotrimeric G protein subunit α (GNAQ) and in its paralog GNA11, which share > 90% peptide sequence identity and strikingly similar effects." (PMID 37966164, 2023). "Activating mutations in the genes coding for G protein subunit alpha q (GNAQ) or G protein subunit alpha 11 (GNA11) are present in approximately 90% of uveal melanoma patients, and the GNA11 mutation rate is significantly dependent on PKC activity." (PMID 37576814, 2023). "Additional mutations in EIF1AX and SF3B1 have been associated with a favourable prognosis subtype of uveal melanoma, whereas mutations in GNAQ/GNA11 are found in more than 90% of patients." (PMID 38201222, 2023).
uveal melanoma (continued). "GNAQ p.Q209 mutations have been implicated in more than 90% of cases of GNAQ-driven uveal melanoma (UM), although, studies conflict regarding the downstream molecular interactions driving cancer formation and progression." (PMID 36405075, 2022). "PLCB4 mutations occur in approximately 5% of uveal melanoma and are mutually exclusive with GNAQ, GNA11, and CYSLTR2 mutations." (PMID 35158973, 2022). "Mutations affecting Q209 in GNAQ were present in 45% of primary uveal melanomas and 22% of uveal melanoma metastases." (PMID 35975235, 2022). "Instead, activating mutations in GNAQ or GNA11 genes occur in 80–90% of uveal melanoma cases in a mutually exclusive pattern." (PMID 35409195, 2022). "The main known oncogenic drivers in uveal melanomas are mutations in the heterotrimeric G-protein alpha subunit GNAQ or its paralog GNA11 (GNAQ/11)." (PMID 35673577, 2022). "For example, >80% of uveal melanomas and ~6% of cutaneous melanomas have mutations in GNAQ/GNA1 proteins, which stimulate RhoA activity and activate YAP/TAZ independent of any alterations in LATS1/272–74." (PMID 35768444, 2022). "In contrast to cutaneous melanoma, mutations in BRAF are very rare in uveal melanoma, whereas mutations in GNAQ and GNA11 are common, and uveal melanoma has a much lower tumor mutational burden." (PMID 35021863, 2022). "Uveal melanoma is the most common primary ocular malignancy in adults, characterized by gene mutations in G protein subunit alpha q (GNAQ) and G protein subunit alpha 11 (GNA11)." (PMID 34830903, 2021). "Significant insight has been gained into the pathways that are altered in uveal melanoma, with mutually exclusive activating mutations in the GNAQ and GNA11 genes being found in over 90% of patients." (PMID 34944815, 2021). "Over 90% of uveal melanomas harbor pathogenic variants of the GNAQ or GNA11 genes that activate survival pathways." (PMID 34533562, 2021). "Typical uveal melanoma-related mutations were found in seven cases (15%): one case with GNAQ p.R183Q, one with GNA11 p.R183C, two with SF3B1 p.R625C/H, and three with BAP1 missense/nonsense supposedly somatic mutations." (PMID 34359736, 2021). "For example, several zebrafish models of uveal melanoma have shown that melanocyte-specific expression of driver mutations GNAQ/GNA11(Q209L) led to considerable changes in the melanocyte biology of the fish." (PMID 32532044, 2020). "Recent experimental studies have demonstrated an essential role for the Hippo-Yes-associated protein (YAP) pathway in GNAQ/GNA11-induced tumorigenesis in uveal melanoma (UM)." (PMID 32277165, 2020). "In uveal melanoma, GNAQ and GNA11 gene mutations are frequently found and prognosis is based on mutation status of BAP1, SF3B1 and EIF1AX genes." (PMID 33396957, 2020). "CYSLTR2-mutated uveal melanoma usually presents an overactivation of the GNAQ pathway and an insensitivity to any ligand." (PMID 32532044, 2020). "Apart from being found in the meninges (59%), in blue naevi (83%), and in a subset of cutaneous melanomas linked to chronic sun-induced damage (3–4%), GNAQ or GNA11 represent driver oncogenes in around 50% uveal melanoma." (PMID 32532044, 2020). "Of 63 Chinese samples with uveal melanoma, we found seven somatic Q209 mutations in GNAQ (11.1%) and 14 Q209 mutations in GNA11 (22.2%)." (PMID 35693877, 2019). "In this report, we demonstrate that Tris DBA palladium is effective in vitro against a panel of human uveal melanoma cell lines with mutations in GNAQ and GNA11." (PMID 31320995, 2019). "Activating mutations of CYSLTR2 (p.L129Q) in uveal melanoma are mutually exclusive and functionally equivalent to mutations in GNAQ/11 (p.Q209)." (PMID 31337866, 2019). "Recently, the most common driver mutations in uveal melanoma have been identified, predominantly in the G-proteins GNAQ." (PMID 31320995, 2019). "It was shown that GNAQ mutation, one of the driver mutation in uveal melanoma, is present in Mel270 cells." (PMID 31065009, 2019).
uveal melanoma (continued). "The predominant mutations present in uveal melanoma are in GNAQ or the mutually exclusive GNA11 gene, which are mutated in 90% of uveal melanomas." (PMID 31046743, 2019). "Among Uveal Melanoma (UM) driver mutations, those involving GNAQ or GNA11 genes are the most frequent, while a minor fraction of tumors bears mutations in the PLCB4 or CYSLTR2 genes." (PMID 31216772, 2019). "Recurrent activating somatic mutation in GNA11 or GNAQ (NM_002067.2: c.626A > T, p.Q209L or NM_002072.3: c.626A > C, p.Q209P, respectively), a typical molecular sign of uveal melanoma, have been detected in all five cases." (PMID 29769598, 2018). "GNAQ mutations have been found in thyroid cancer and GNAQ/GNA11 mutations are able to initiate human uveal melanoma." (PMID 29324665, 2018). "The molecular study of the urinary bladder tumor specimen identified mutation of the GNAQ gene, which has been suggested to be an early molecular event in the pathogenetic course of over 80% of uveal melanomas." (PMID 29085693, 2017). "The conclusion of these studies was that more than 80% of uveal melanomas had somatic mutations in GNAQ or GNA11, implying that MAPK activation is a major contributor to the development of uveal melanoma." (PMID 29156643, 2017). "Somatic mutations in the GNAQ gene have been identified in 83% of cases of human blue nevi, 50% of MABNs, and 46% of uveal melanomas." (PMID 27057633, 2016). "Mutations in BRAF, KIT and NRAS are rarely seen in uveal melanoma; however more than 80 percent of uveal melanomas have mutations in GNAQ or GNA11." (PMID 26334521, 2015). "As noted, tumours dependent on the Ras/Raf/MEK/ERK pathway include uveal melanomas harbouring oncogenic GNAQ/GNA11 mutations." (PMID 26059332, 2015). "Onken and his colleagues reported that 49% of the uveal melanomas harbored activating mutations in GNAQ." (PMID 25280020, 2014). "Activating mutations in GNAQ and GNA11, encoding members of the Gα(q) family of G protein α subunits, are driver oncogenes in uveal melanoma." (PMID 24743024, 2014). "Van Raamsdonk and her colleagues found somatic mutations in GNAQ or GNA11 in 83% of the globes with uveal melanomas." (PMID 25280020, 2014). "In Caucasian patients with uveal melanomas, the reported GNAQ mutation frequency varied between 36% and 53%." (PMID 25280020, 2014). "The identical p.Arg183Gln mutation in GNAQ, when occurring in melanocytes later in life, is a frequent driver mutation in uveal melanoma (OMIM #155720), highlighting the importance of both the location and timing of the mutation." (PMID 25513881, 2014). "The recent identification of activating mutations in the G-alpha protein from the GNAQ gene in uveal melanoma has provided a key insight into potential strategies in which to target uveal melanoma cell growth and survival." (PMID 24551032, 2014). "Mutations in GNAQ cause Sturge-Weber syndrome and port-wine stain birthmarks as well as uveal melanoma." (PMID 25513881, 2014). "Uveal melanoma growth is driven by gain-of-function mutations in GNAQ or GNA11 oncogenes, encoding persistently active G protein α subunits of the Gq family." (PMID 25526026, 2014). "Mutant alleles of the GNA11 or GNAQ genes, which are highly specific for uveal melanoma, were identified in cfDNA of 9 of 22 (41%) patients." (PMID 23634288, 2013). "In contrast, genetic alterations in uveal melanoma such as GNAQ and GNA11 mutations were also found in selected cases of cutaneous melanoma and are frequently found in blue nevi (benign cutaneous melanocytic tumors)." (PMID 23694694, 2013). "In a previous work we reported BRAF mutations in 30% of skin melanomas and GNAQ gene mutations in 36% of uveal melanomas." (PMID 23904987, 2013). "In uveal melanoma a different set of genes shows recurrent mutations, including GNAQ and GNA11, with activating mutations as well as in BAP1 showing inactivating mutations." (PMID 23694694, 2013).